POU5F1 (POU class 5 homeobox 1)
Diseases named in the same sentence as POU5F1 in open-access papers (continued):
Sharing a sentence is not in itself a finding about the gene and the disease.
cancer (1,436 papers, 2006 to 2026). A tumor composed of atypical neoplastic, often pleomorphic cells that invade other tissues. "Octamer-binding transcription factor 4 (OCT4), encoded by the POU5F1 gene, is a well-recognized hallmark of pluripotency in both embryonic and quiescent adult cells and plays a key role in cancer." (PMID 40986050, 2025). "In this way, we also found the mRNA levels of cancer stemness-associated molecules, including POU5F1, Slug and ABCG2, were significantly decreased by melatonin treatment in both LoVo and DLD-1 cell lines." (PMID 34671196, 2021). "The OCT-3/4 protein (octamer-binding transcription factor-3/4) encoded by the POU5F1 gene is more recently treated as an important surface marker for the subpopulation of undifferentiated cancer-initiating cells." (PMID 31915501, 2019). "It has also been considered that POU5F1/Oct-4 is associated with cancer, since there are many similarities between ESCs and cancer cells." (PMID 26931354, 2016). "We chose five lncRNAs (HOTAIR, HOXA-AS-2, lincRNA—ROR, MALAT1, and ANRIL) and three mRNA Homeobox A13 (HOXA13), SRY-box 2 (SOX2) and POU class 5 homeobox 1 (POU5F1/OCT4) implicated in a range of cancers, including UBC." (PMID 26800519, 2016). "Oct4 protein encoded by POU5F1 plays a pivotal role in maintaining the self-renewal of pluripotent stem cells; however, its presence in cancer cells remains controversial." (PMID 25625591, 2015). "NANOG and POU5F1 are well-known transcription factors that play critical roles in maintaining the pluripotency of embryonic stem cells, and their expression has been associated with poor prognosis in various cancers, including PDAC." (PMID 40699634, 2025). "The observed expansion of OLFM4+ and POU5F1+ transient amplifying cells may contribute to disease progression and increased cancer risk." (PMID 33570127, 2021). "Our study identified POU5F1 as a pan‐cancer gene that could not only be a prognostic and diagnostic biomarker in various cancers, especially in LIHC, but functionally carcinogenic in LIHC." (PMID 32978904, 2020). "POU5F1 as a pan‐cancer gene could be a prognostic and diagnostic biomarker in various cancers, especially in LIHC." (PMID 32978904, 2020). "POU5F1 (OCT4) is implicated in cancer stem cell self‐renewal." (PMID 31012189, 2019). "POU5F1 is a key regulator of self-renewal and differentiation in embryonic stem cells and may be associated with initiation, promotion, and progression in cancer." (PMID 26824036, 2015). "The POU homeodomain transcription factor Oct4 (Pou5f1) is an essential mediator of the embryonic stem cell state and has been implicated in lineage specific differentiation, adult stem cell identity, and cancer." (PMID 17579724, 2007). "In addition, loss of function of POU5F1 remarkably restrains propagation, metastasis, and aggression of cancer stem cells through inhibition of the PI3K/Akt pathway, from which we could expect POU5F1 to be an underlying target for cancer therapy." (PMID 32978904, 2020). "In addition, low expression of POU5F1 was associated with shorter cancer-related survival and might be a novel biomarker for BLCA." (PMID 32983230, 2020). "However, the observation that POU5F1 is expressed in TGCC, and may be somatically mutated in other cancers, suggests that genetic variation in POU5F1 could conceivably alter protein expression or activity, thereby influencing risk of TGCC." (PMID 18254969, 2008). "These analyses revealed statistically significant survival disparities in patients with altered POU5F1 expression, highlighting its potential as a therapeutic target in cancers." (PMID 41465103, 2025). "POU5F1, on the other hand, has been implicated in epithelial–mesenchymal transition (EMT), a process that endows cancer cells with enhanced migratory and invasive properties, facilitating metastasis." (PMID 40699634, 2025).
cancer (continued). "Given its central role in cell identity and proliferation, POU5F1 is a subject of intense study, not only for its fundamental role in cell biology but also for its potential as a target in cancer treatment strategies." (PMID 41465103, 2025). "Pluripotency-associated factors such as OCT4 (POU5F1), SOX2, and NANOG are frequently implicated in dedifferentiation and cancer stem cell (CSC) maintenance, allowing tumor cells to regain developmental plasticity." (PMID 40722714, 2025). "POU5F1 plays a crucial role in the self-renewal and pluripotency of embryonic and germline stem cells, as well as embryonic cancer cells." (PMID 40927570, 2025). "Specifically, we suggested that the SMAD complex (SMAD2/3/4) positively interacts with OCT4 (POU5F1), one of the essential markers of cancer stemness, as indicated by network analysis." (PMID 38245623, 2024). "OCT4 is a member of Pit-Oct-Unc transcription factor family, encoded by POU5F1 gene, which is overexpressed in CSCs of various cancers." (PMID 38561775, 2024). "POU5F1 has been reported as a biomarker in both undifferentiated cells and several cancer cells, suggesting shared characteristics between these cell types." (PMID 38951817, 2024). "Loss of cancer differentiation from luminal-like to stem-like is mediated by the activation of stem cell transcription factors (scTF) such as LIN28A, NANOG, POU5F1 and SOX2." (PMID 38595814, 2024). "A similar effect is observed in Huh7-cells, where cirrhotic hydrogels induced expression of SNAI1 and POU5F1, two important markers for cancer stemness." (PMID 36639512, 2023). "Previous research has thoroughly explored the oncogenic phenotypes of POU5F1 in various human cancers, including BCa." (PMID 37325625, 2023). "Intense POU5F1 expression was associated with disease progression, greater metastasis, and shorter cancer-related survival as compared to tumors with low or moderate POU5F1 expression." (PMID 37627900, 2023). "Flow cytometric analysis showed that the population of POU5F1-positive cells was also detected in 2DOs as cancer cells and differed from previously reported CRC stem cell marker-positive cells, including those with the markers, CD133, CD44, CD24, and LGR521." (PMID 37996567, 2023). "The third cluster of the built PPI network is well represented by transcriptional factors e.g., such as SOX2, NANOG and POU5F1/OCT4, which are considered cancer stem cell (CSC) markers." (PMID 37445716, 2023). "First, in adult stem cells or cancer cells, Pou5f1 up-regulates the expression of CCND by binding to the octamer motif in the CCND promoter region, thereby promoting the G1/S transition." (PMID 36770809, 2023). "A small population POU5F1-positive circulating tumor cells (CTC) have cancer stem cell abilities and contribute to colorectal cancer aggressiveness and metastasis." (PMID 37996567, 2023). "Another cancer stem cell marker with a substantial impact on the platinum sensitivity of OC cells was POU5F1." (PMID 37628927, 2023). "Sorted POU5F1-expressing cells from 2DOs have cancer stem cell abilities and abundantly form liver metastases in vivo." (PMID 37996567, 2023). "As revealed by pan-cancer analysis, POU5F1 can be used to diagnose and predict the prognosis of different cancers in particular functional carcinogenicity of LIHC." (PMID 36457341, 2022). "Functional analyses strengthen the biological and molecular relevance of POU5F1/OCT4 in controlling carcinogenesis and cancer stem cells (CSCs), pointing to yet obscure cellular and molecular features likely shared between carcinogenesis and reprogramming." (PMID 35892595, 2022). "DNA methylation at the MYC-binding elements in the POU5F1 locus is involved in regulating POU5F1 expression in cancer cells." (PMID 36564568, 2022). "Data studies have indicated that CGA reduces the expression of self-renewal related stem cell marker genes Nanog, POU5F1, Sox2, CD44, and Oct4, and inhibits the migration of cancer cells." (PMID 35845802, 2022).
cancer (continued). "To verify that the spheres in our setup were enriched in cancer stem cells, we tested the expression of the stemness-related transcription factors POU5F1 (Oct4), SOX2, CD44, PROM1 (CD133), and NANOG in spheres and adherent cells 72 h after seeding." (PMID 34832951, 2021). "GSEA indicated that POU5F1 participated in multiple cancer‐related pathways and cell proliferation pathways." (PMID 32978904, 2020). "Subgroup analyses were implemented for OS and DFS to clarify the connection between POU5F1 expression and cancer type, analysis type, sample size, and detection method." (PMID 32978904, 2020). "First, we performed a meta‐analysis and trial sequential analysis (TSA) with a large sample size to evaluate the significance of POU5F1 for survival prognosis in various cancers." (PMID 32978904, 2020). "In summary, our study identified POU5F1 as a pan‐cancer gene with significant prognostic value in various cancers, especially in LIHC." (PMID 32978904, 2020). "Analysis revealed that genes associated with cancer stem cells, such as POU5F1 (OCT4), SOX2, NANOG, BMI1, BMP2, CD44, SOX9, and ALDH1 were markedly upregulated in enzalutamide resistant cells." (PMID 33339129, 2020). "The amalgamative results indicated that elevated POU5F1 was associated with poor OS, DFS, DSS, and RFS in various cancers." (PMID 32978904, 2020). "The prognostic and clinicopathological significance of POU Class 5 Homeobox 1 (POU5F1) among various cancers are disputable heretofore." (PMID 32978904, 2020). "In particular, TSA confirmed that the sample size of current studies has far exceeded the APIS, suggesting it was quite credible to draw a conclusion that elevated POU5F1 was apparently connected with shorter OS in various cancers." (PMID 32978904, 2020). "This, in turn, induces expression of core stem cell genes NANOG, SOX2 and POU5F1, leading to increased cancer stemness and tumorigenic potential." (PMID 32235004, 2020). "Meta‐analysis was utilized to investigate the impact of POU5F1 on prognosis and clinicopathological parameters in various cancers." (PMID 32978904, 2020). "Transcription factors, which play a critical role in reprogramming cells to pluripotency have also been identified in human cancers, including PCa and include POU5F1, SOX2 and ALDH160." (PMID 32647229, 2020). "It is well documented that POU5F1 is highly expressed in many cancer types, and nucleus POU5F1 contributes to tumorigenicity and maintaining stemness of cancer stem cells." (PMID 31046781, 2019). "As the most typical stemness transcription factor, POU class 5 homeobox 1 (POU5F1, also known as OCT4) is widely expressed in almost all kinds of stem cells, including embryonic stem cells and cancer stem cells." (PMID 31375149, 2019). "Taken together, these findings clarify that POU5F1 plays a crucial role in maintaining the CSC phenotype in multiple human cancer types." (PMID 29568377, 2018). "From studies of cancer stem cells, the transcription factor OCT4, encoded by the POU5F1 gene, was found to be a critical factor for self- renewal and maintenance of pluripotency of stem cells." (PMID 27551335, 2016). "Some of these pseudogenes detected in certain cancer cell lines and cancer tissues are involved in the regulation of POU5F1 gene activity and are correlated with poor prognosis of human cancer." (PMID 25625591, 2015). "In these other types of cancer higher NANOG and POU5F1 expression has been associated with greater resistance to chemotherapeutic agents and drug resistance has variously been attributed to mesenchymal-like characteristics and increased drug efflux." (PMID 24475288, 2014). "Oct-4/POU5F1 is a member of the POU family of transcription factors and its expression had been associated with cancer stem cells." (PMID 24070327, 2013).
cancer (continued). "Alterations in the function or levels of POU5F1 can disrupt these processes and may contribute to the development of cancer, as this gene can act as an oncogene when improperly regulated." (PMID 41465103, 2025). "Examples include overexpression of the pluripotency- and apoptosis-related POU5F1 (OCT4) (i.e., TGCT-15.6.3.P.3.0.0.2.4.2), SOX2 (i.e., LUSC-2293.6.3.P.3.62.30.1.4.3), and NANOG (i.e., TGCT-4.6.3.P.3.0.0.2.4.1) genes in various cancer types associated with stemness and poor prognosis." (PMID 41048343, 2025). "Conversely, SOX2 and POU5F1 expression levels progressively increased with advancing cancer stage." (PMID 40279337, 2025). "Additionally, the lack of expression of pluripotency antibodies (Nanog, SOX2, and OCT4) coupled with POU5F1's normal molecular arrangement disputes the cancer stemness paradigm in MEC." (PMID 40478494, 2025). "Given that the GSC state is not a stable clonal subpopulation but rather a plastic state induced by the tumor microenvironment, we scored cells based on classic GSC markers (PROM1, SOX2, NES, OLIG2, BMI1, NANOG, POU5F1) and defined the top 2% of cancer cells with the highest stemness scores as GSCs." (PMID 41041071, 2025). "We identified BMI1, MYC, NANOG, and OCT3/4 (POU5F1 gene) pluripotency markers as the most prominent transcription factors associated with HDAC2 gene expression, highly supporting HDAC2’s association with cancer stemness." (PMID 39063083, 2024). "Intriguingly, METTL3 and POU5F1 (Oct4) were reported to affect miR‐1246 levels in cancer cells." (PMID 38342611, 2024). "Bioinformatics analysis shows that POU5F1 is overexpressed in a variety of cancers." (PMID 36770809, 2023). "Also, the activation of core pluripotency transcription factor machinery, namely OCT4 (encoded by POU5F1), SOX2, Myc, or NANOG, is frequently observed in cancer stem cell-like tumor types and associated with worse patient survival." (PMID 36674511, 2023). "The POU5F1 (OCT4) is a transcription factor that plays a key role in embryonic development and stem cell pluripotency, and it has been linked to several forms of cancer." (PMID 33414392, 2021). "Except for the POU5F1 gene (OCT4), which is a cancer stem cell marker and its expression was found to be associated with worse outcome, the role of the other seven genes in TNBC tumorigenesis, as well as their prognostic significance, is not yet well identified." (PMID 33304345, 2020). "Elevated POU5F1 was associated with poor OS, DFS, RFS, and DSS in various cancers." (PMID 32978904, 2020). "Consistent with its role as a regulator of stemness in normal and cancer stem cells, we did not observe changes in either apoptosis or cell cycle in response to POU5F1/OCT4 knockdown." (PMID 30074477, 2018). "However, ATP-binding cassette sub-family G member 2 (ABCG2) and OCT-4 (also known as POU5F1 (POU family of transcription factors, class 5, factor 1)) are accepted CSC markers in numerous cancers and are linked with prognosis." (PMID 28212529, 2017). "To date, high expression level of POU5F1 has been detected in various types of cancer cells." (PMID 26824036, 2015). "In order to determine transcription factors in cancer-associated fibroblast activation, which play a role in cell proliferation and cancer progression, we evaluated the expression of several transcription factors, including SOX9, POU5F1, ZEB1, JUN, and FOS in the HRTPT cell line exposed to arsenite." (PMID 40699854, 2025). "Additionally, a separate literature source has reported a negative correlation between POU5F1 expression and cancer differentiation in GC, whereby higher levels of POU5F1 expression are linked to shorter patient survival rates." (PMID 38062041, 2023). "We observed enrichment of human embryonic stem cell pluripotency genes along with transcriptional regulation of pluripotent stem cells that might lead to activation of POU5F1 (OCT4), SOX2, CD44, NANOG, and other genes associated with self-renewal and drug resistance of cancer cells." (PMID 33339129, 2020).
cancer (continued). "For example, POU5F1 (also known as OCT4), functioning in stem cell pluripotency and embryonic development, was hypomethylated in 98.13% of the 268 cancer samples, which is concordant with the findings that this gene is overexpressed in CRC and may contribute to CRC development." (PMID 28537885, 2017). "Further investigation can be conducted to assess the impact of specific TFs, such as POU5F1 and NANOG, in cancers occurring in the testis and lung." (PMID 41465103, 2025). "The C2-E.T cluster exhibited concurrent high expression of POU5F1 and CD44, recognized markers of cancer stem cells (CSCs), indicating the presence of CSCs attributes in the C2-E.T cluster." (PMID 38191424, 2024). "In this study, we examined the expression of the pluripotency genes (NANOG, SOX2, and POU5F1) and the ALDH1A1 gene in ER+ BC tumors across three large cancer datasets." (PMID 38400679, 2024). "This subpopulation demonstrated high expression levels of the cancer stem cell markers POU5F1 and CD44 (POU5F1hiCD44hiE.T), with the transcription factor POU5F1 regulating the expression of SPP1." (PMID 38191424, 2024). "First, we measured cancer stem-like phenotype markers, including NANOG, NOTCH, POU5F1(OCT3/4), SOX2, and BMI-1." (PMID 39728923, 2024). "First, we observed that DVL2 directly regulates expression of genes involved in cancer hall marks, CCND1, VEGFA and POU5F1." (PMID 36809986, 2023). "In the present study, we found that the STAT3 signaling pathway played an important role in mediating the function of IL20RB in promoting cancer stemness and chemoresistance, and IL20RB-STAT3 signaling promoted the expression of NANOG, SOX2 and POU5F1." (PMID 38098005, 2023). "The doxorubicin treatment displayed a favorable gene signature among surviving cancer cells with low proliferation (MKI67) and pluripotency features (NANOG, POU5F1), in comparison to 5-fluorouracil showing low proliferation but increased pluripotency." (PMID 38124067, 2023). "The varied enrichment of OCT4 (POU5F1), SOX2, and NANOG in different types of cancer cells demonstrated the diversity of CSCs localization." (PMID 36451812, 2022). "POU5F1 expression is controlled by several transcription factors, such as HIF1 and MYC, in cancer cells." (PMID 36564568, 2022). "Enhanced expressions for cancer stem cell markers Sox2, POU5F1(Oct4), Nanog, ALDHA1 and CD133 were observed in dormant and reactivated cancer cells after treatment of cisplatin." (PMID 36402751, 2022). "This concept was further supported by the positive correlation of CEP192 with characteristic onco-fetal genes, also known as cancer stem cell markers, including CD24, SOX9, CD47, and POU5F1 (OCT4)." (PMID 36238304, 2022). "E-cadherin can suppress cancer stemness by regulating the expressions of pluripotent genes (MYC, NESTIN, POU5F1, and SOX2) via the activation of Wnt/β-catenin signaling." (PMID 33917482, 2021). "This was confirmed by our analysis since all candidate CNVs that we have identified and that were found to affect the cancer genes PMS2, APC2, POU5F1, KANSL1, DOCK8 and TMTC3 are part of this category." (PMID 33503040, 2021). "This study revealed that HNF1A is downstream of POU5F1 and high HNF1A expression in cancer tissue is an independent marker of poor prognosis, which is related to CRC recurrence and patient mortality." (PMID 33990627, 2021). "Further PCR analysis also indicated decreased mRNA levels of cancer stem cell biomarkers in 25 μM AB4 treated HCT116/FU sphere cells, including LGR5, CD133, CD24 and POU5F1." (PMID 34890366, 2021). "Within community 2, we also identified increased expression of regulators of cell proliferation (CENPE, MKI67, TOP2A, UBE2C, guanine), cancer, and pluripotency (DNMT3B, DPPA4, MYC, POU5F1, CRABP2)." (PMID 33771987, 2021). "Compared with monolayer-culture GBM cell lines, cancer stem cell (CSC) markers such as SOX2, PROM1, POU5F1, MSI1, FUT4, and CXCR4 were upregulated in the spheroids." (PMID 34638384, 2021).